INS (insulin)
Diseases named in the same sentence as INS in open-access papers (continued):
Sharing a sentence is not in itself a finding about the gene and the disease.
Insulin resistance (continued). "Nevertheless, previous studies have not demonstrated any linkage between donation to fasting glucose, hemoglobin A1C, insulin concentrations, or the calculated Homeostasis Model Assessment – Insulin Resistance -HOMA-IR." (PMID 30704441, 2019). "Understanding the molecular components of insulin signaling is relevant to effectively manage insulin resistance." (PMID 31624249, 2019). "With increasing body weight insulin homeostasis is impaired, leading to hyperinsulinemia and insulin resistance." (PMID 31076634, 2019). "Enhanced levels of cortisol and other catecholamines which antagonize insulin action on glucose metabolism in depressed people can result in insulin resistance." (PMID 31260504, 2019). "Insulin resistance is defined as the reduced responsiveness of target tissues to normal insulin levels and is widely accepted as the primary mechanism of the pathophysiology of MetS." (PMID 31824416, 2019). "Using the insulin resistance homeostasis model, glycine concentrations were found to be positively correlated with insulin sensitivity and inversely correlated with insulin resistance." (PMID 31208147, 2019). "When insulin resistance reaches higher levels, the insulin compensatory secretion becomes insufficient, blood glucose rises, and GDM occurs." (PMID 30805369, 2019). "Adolescents with high body fat presented higher values of anthropometric measurements (WC, NC, and WtHR), gynoid and android BF%, and higher concentrations of insulin, insulin resistance (IR), and leptin." (PMID 31933541, 2019). "Hypoglycemia occurs quite often in patients with insulin resistance, type 1 and even type 2 diabetes after insulin treatment and/or following intense exercise." (PMID 30996341, 2019). "DM is characterized by the elevation of blood glucose due either to a defect in insulin synthesis, secretion, binding to receptor, or an increase of insulin resistance." (PMID 31480505, 2019). "Surprisingly, the severe insulin resistance that was observed in AG male mice prior to the initiation of MitoQ treatment was abolished, indicating either an improvement in insulin action in the AG mice or a deterioration of insulin action in the YG mice." (PMID 30706674, 2019). "As vaspin improves insulin resistance an increase in concentration will have the effect of improved fetal insulin utilization." (PMID 30325336, 2019). "There are many theories relating to insulin resistance, such as inhibition of proximal insulin signaling via either lipid mediated activation of protein kinase C or altered release of adipocytokines from expanded and inflamed adipose tissue." (PMID 31920989, 2019). "T2DM is characterized by hyperglycemia due to impaired insulin secretion from pancreatic β-cells and insulin resistance in insulin-sensitive tissues such as skeletal muscle, liver, and adipose tissue." (PMID 31817726, 2019). "HFD-induced mice were employed to establish insulin resistant mouse models in order to elucidate the role of Saa1 in insulin resistance in vivo." (PMID 31060494, 2019). "Obesity induces insulin resistance in peripheral insulin target tissues, and adipose tissue is considered to play a central role in insulin resistance." (PMID 31455007, 2019). "Pulses (i.e., lentils, chickpeas, peas, beans) have a low glycemic index and have been used in clinical populations to improve insulin sensitivity and reduce insulin resistance." (PMID 31461862, 2019). "PA has been shown to directly impair insulin signaling in cultured hepatocytes and has been previously used to induce insulin resistance in HepG2 cells." (PMID 31828133, 2019). "In accordance with their insulin resistance, serum insulin concentrations remained significantly higher in Ubi-LepRNull mice, compared to Ubi mice." (PMID 30694175, 2019). "In T2D, both insulin resistance and a suppression of adaptive increased insulin secretion are intrinsic properties of SkM that can contribute to the full T2D phenotype." (PMID 32038288, 2019).
Insulin resistance (continued). "Obesity and type 2 diabetes (T2DM) are characterized by a blunted metabolic response to insulin, and strongly manifests in skeletal muscle insulin resistance." (PMID 30912283, 2019). "One study conducted in Pakistan revealed a higher frequency of hyperinsulinemia (fasting insulin level > 10) and insulin resistance relative to the rates reported in studies on white Caucasian women with PCOS." (PMID 31603907, 2019). "Tau has recently been characterized as an important regulator of insulin signaling, with evidence linking Tau to brain and peripheral insulin resistance and beta cell dysfunction." (PMID 30804755, 2019). "It protects myocytes from insulin overstimulation but also contributes to insulin resistance by slowing down insulin entry into the muscle interstitium, a double-edged sword." (PMID 30699907, 2019). "In humans, higher fasting levels of insulin and insulin resistance measured by homeostatic model assessment for insulin resistance (HOMA) positively correlate with adipose tissue NPRC expression." (PMID 31269783, 2019). "In vivo research presents data that are conflicting, some suggesting that IH induces insulin resistance while others show improvements in insulin sensitivity." (PMID 31557884, 2019). "Values within the highest quartile are recommended and often used to characterize insulin resistance among the total distribution of a surrogate insulin index." (PMID 31694444, 2019). "We assessed the prevalence of glucose intolerance including impaired fasting glucose and/or impaired glucose tolerance, as well as insulin secretion and insulin resistance using the homeostasis model assessment, and compared the results between the two groups." (PMID 31252561, 2019). "In contrast, fasting insulin and homoeostatic model assessment for insulin resistance (HOMA‐IR) were significantly increased in the CHC group consistent with systemic insulin resistance." (PMID 30586166, 2019). "Probiotic supplementation (group 3) reduced weight gain, and there were positive effects on the levels of fasting plasma glucose, insulin, homeostatic model assessment-insulin resistance, triglycerides, inflammatory markers, leptin, and chemerin." (PMID 31284705, 2019). "In recent years, insulin resistance in pancreatic α cells has been proposed; moreover, the relationship between insulin and glucagon has been gaining considerable attention." (PMID 31357734, 2019). "Branched chain amino acids (BCAA) can impair insulin signaling, and cardiac insulin resistance can occur in the failing heart." (PMID 31277657, 2019). "Many studies have reported that the high-fat diet fed rats develop insulin resistance and low-dose streptozotocin administration has been known to induce mild impairment of insulin secretion which mimics the natural history of type 2 diabetes." (PMID 31142215, 2019). "Since metformin primary actions significantly reduce the circulating glucose and plasma insulin, hence, it improves insulin resistance in peripheral tissue." (PMID 31831021, 2019). "High glycemic index foods induce an exaggerated insulin response, which can increase body fat and weight, and lead to insulin resistance, and eventual exhaustion of endocrine pancreatic function and insulin release." (PMID 30865634, 2019). "Researchers studied fasting glucose and insulin and consequently insulin resistance expressed as insulin resistance by the homeostasis model assessment (HOMA-IR)." (PMID 31886278, 2019). "The use of HOMA-IR to assess insulin resistance in individuals specifically on insulin therapy warrants further investigation." (PMID 31065243, 2019). "In vivo and in vitro studies have demonstrated that an excess level of OS results in impaired insulin secretion and insulin resistance." (PMID 31163689, 2019). "Nevertheless, we observed that the mean value of fasting insulin as well as of the insulin resistance index (homeostatic model assessment for insulin resistance [HOMA-IR]) was slightly reduced." (PMID 31138673, 2019).
Insulin resistance (continued). "Increased plasma levels of TNFα and IL6 are associated with insulin resistance (Shoelson, Herrero, & Naaz, 2007), inconsistent to observations made here where HFD‐fed Park2 KO mice were more insulin sensitive despite increased plasma TNFα and IL6 levels." (PMID 31724300, 2019). "In the McAuley and revised McAuley index, insulin resistance is determined by measures based on fasting insulin and triglyceride levels." (PMID 30866603, 2019). "The pathogenesis of T2D is insulin resistance, where the body has a low reaction to insulin even though insulin levels are normal or higher." (PMID 31067805, 2019). "Decreased insulin secretion and increased insulin resistance are important to the pathophysiologic mechanism behind NODAT." (PMID 31252561, 2019). "Type 2 diabetes mellitus (T2DM), a non-communicable metabolic disease characterized by high blood glucose levels, results from impaired insulin secretion, insulin resistance or a combination of both." (PMID 31721790, 2019). "Insulin resistance is a pathological state in which tissues have a decreased sensitivity to insulin, leading to a compensatory rise in circulating insulin to maintain normal blood glucose levels." (PMID 30786864, 2019). "Insulin resistance is a pathological condition characterized by the inability of insulin to regulate glucose and lipid metabolism in peripheral tissues even when insulin concentrations in the blood are elevated." (PMID 31035653, 2019). "GLP-1 is known to stimulate insulin production by islet β-cells, it counteracts insulin resistance, improves tolerance to peripheral glucose, has anti-inflammatory properties." (PMID 30836679, 2019). "This inactivation resulted in insulin resistance at the central nervous system (CNS) but mice also developed obesity, combined with hyperphagia, an increase of leptin and insulin concentrations in plasma, as well as the development of hypertriglyceridemia." (PMID 31551756, 2019). "In contrast, T2DM is characterized by insulin resistance, impaired insulin reaction of the target cells, and dysregulated insulin secretion." (PMID 31500224, 2019). "Inflammation has a vital role in the progression of DM and is therefore related to increased insulin resistance and decreased response in insulin target tissues." (PMID 31708869, 2019). "Firstly, in early CKD, less insulin secretion and more insulin resistance requires patients to need a higher insulin dose or more medications for sugar level control." (PMID 31261624, 2019). "In this scenario, hyperinsulinaemia downregulates tissue insulin action (insulin-induced insulin resistance)." (PMID 31489455, 2019). "Insulin, total testosterone, fasting glucose, homeostasis model assessment, and insulin resistance index in women with POR decreased when compared with PCOS." (PMID 31897389, 2019). "The HOMA-IR method is widely used for assessing insulin resistance in clinical trials and epidemiological studies, improvement of which indicates enhanced insulin sensitivity." (PMID 30926892, 2019). "After 12 weeks and 24 weeks only LFD-fed WT mice showed preserved insulin sensitivity, while the other groups displayed insulin resistance." (PMID 30813929, 2019). "Our main objective was to compare marginally LBW and NBW children at 3.5 and 7 years with respect to glucose, insulin, homeostatic model assessment for insulin resistance (HOMA-IR), lipid status, and high sensitive C-reactive protein (hs-CRP)." (PMID 31002705, 2019). "Patients with hypoglycemia of Groups 1 had low insulin secretion and were high among insulin users, those of Groups 2 had low homeostasis model assessment of insulin resistance (HOMA-IR)." (PMID 30815039, 2019). "Interleukin-6 is a cytokine secreted by adipose tissue being involved in signaling pathways of inflammation and insulin signaling in various tissues and cell types and high circulatory level had been correlated with insulin resistance and type 2 diabetes." (PMID 30605486, 2019).
Insulin resistance (continued). "In summary, the current results further demonstrate that in addition to markedly improving muscle insulin resistance in obese human subjects with T2D, aerobic exercise training also improves insulin-mediated suppression of EGP." (PMID 31474750, 2019). "We recently described that higher insulin levels, together with higher glucose concentration, simulate insulin resistance found in obese patients, and reduced the ability of NPs to induce lipolysis and the thermogenic pathway." (PMID 30634533, 2019). "In these figures, insulin resistance, obesity, lipids and blood pressure are latent independent variables, and glucose, insulin, BMI, WHR, TG, HDL, SBP, DBP were observed indicators." (PMID 31801522, 2019). "Insulin resistance and insulin response are highly correlated since majority of the insulin-resistant individuals are either in the highest insulin response quartile or the second highest." (PMID 31664994, 2019). "Adipose tissue inflammation was considered a key factor in the pathogenesis of insulin resistance and potential β-cell-related autoinflammation, which disturbed insulin secretion in DM." (PMID 30779804, 2019). "The overestimation of the insulin sensitivity index (k2) for very high insulin resistance patients is due to the absence, in the Compact Model, of the term representing glucose renal elimination, which is instead present in the Extended Model." (PMID 30768604, 2019). "Plasma glucose and in particular insulin levels and insulin resistance, as assessed by HOMA-IR, were all elevated in obese WT mice, with no significant changes in Nlrp3−/− and Asc−/− (Pycard−/−) mice." (PMID 31379826, 2019). "Whereas earlier work (2002) in post-menopausal women with a slightly higher dose of isoflavones (132 mg) showed decreased HbA1c, fasting insulin and reduced insulin resistance as measured by HOMA-IR." (PMID 31013914, 2019). "Lower values indicate high insulin sensitivity; whereas higher values indicate low insulin sensitivity or insulin resistance." (PMID 31443279, 2019). "Aldosterone increases insulin resistance through inhibition of insulin signaling and insulin-stimulated glucose uptake via glut-4 translocation in adipocytes, skeletal muscle, and vascular smooth muscle cells." (PMID 31035479, 2019). "After 8 weeks, oral glucose response and insulin response indicated insulin resistance in H rats compared to C rats." (PMID 31906096, 2019). "Insulin resistance (IR) and blood glucose and insulin responses to a Mixed Meal Tolerance Test (MMTT) were assessed before (PRE), 20 h and 70 h after (POST) the final HIIT session." (PMID 31827806, 2019). "Cardiometabolic biomarkers (glucose, insulin, homeostasis model assessment-estimated insulin resistance (HOMA-IR), HOMA β-cell function, and leptin) and RBC hemorheological parameters (RBC deformability and aggregation) were analyzed." (PMID 31835508, 2019). "SOCS1 and SOCS3 act as negative regulators in insulin signaling and serve as one of the missing links between insulin resistance and cytokine signaling." (PMID 31717271, 2019). "As overt T2D is characterised by hyperglycaemia due to peripheral insulin resistance together with impaired pancreatic β-cell function, we assessed the effect of AF on insulin sensitivity in a STZ-induced hyperglycaemic animal model." (PMID 31680948, 2019). "Disruption of insulin secretion in β-cells has also been shown to affect insulin sensitivity, and insulin secretion is unable to cope with insulin resistance, triggering glucose intolerance." (PMID 31426858, 2019). "The increase in ROS and proinflammatory cytokines impairs the insulin signalling pathway and activates the NF-κB pathway, perpetuating an inflammatory and oxidative environment, prolonging insulin resistance and, in a certain way, atherosclerosis." (PMID 31354915, 2019).
Insulin resistance (continued). "There were no changes in weight, BMI, alanine aminotransferase, aspartate aminotransferase, glucose, insulin, homeostatic model assessment–insulin resistance score, triglycerides or NEFA following the 2‐week study period in either group." (PMID 31687174, 2019). "Heart-specific Bmal1-/- knockout mice show decreased heart function, systemic insulin resistance and decreased insulin-induced AKT phosphorylation in the liver." (PMID 31139087, 2019). "It is well known that GLP-1 stimulates insulin production by islet β-cells, counteracts insulin resistance, improves peripheral glucose tolerance, and has anti-inflammatory properties." (PMID 31671663, 2019). "Patients with impaired fasting glucose had significantly higher levels of insulin and more pronounced insulin resistance compared to patients with normoglycemic status." (PMID 31046690, 2019). "The major part of insulin-stimulated whole-body glucose is disposed in skeletal muscle, which plays an important role in the pathogenesis of insulin resistance." (PMID 31591391, 2019). "A recent meta analysis used gold standard insulin clamp technique to evaluate the degree of insulin resistance in PCOS." (PMID 31526389, 2019). "Those with insulin resistance had stronger correlations between FetA change and BMI change than individuals with insulin sensitivity." (PMID 31080625, 2019). "Activation of insulin-dependent IRS-1-Akt-AS160 consequence was evaluated for the insulin-resistance according to increasing salt treatment." (PMID 30621146, 2019). "Network analysis revealed the complexity of T2DM_CAD that linked to several inflammatory and insulin resistance pathways like cytokine receptor, Jak-STAT, PI3K-Akt, adipocytokine and insulin signaling pathways." (PMID 30674322, 2019). "This GLP-1 can then bind to receptors on islet β-cells and increase insulin secretion, as well as improving the sensitivity of peripheral tissues to insulin, thereby ameliorating insulin resistance." (PMID 31293553, 2019). "In general, insulin resistance is a condition in which classical insulin target organs have decreased insulin sensitivity resulting in decrease of glucose uptake." (PMID 31357734, 2019). "IGT is a strong predictor of diabetes onset within the next few years and mainly represents failure of postprandial insulin secretion and/or peripheral insulin resistance." (PMID 31717901, 2019). "Obesity results in insulin resistance and β-cell dysfunction, which are unable to fully compensate for the reduced insulin sensitivity of liver tissue, adipose tissue, and skeletal muscle, triggering T2DM." (PMID 31340585, 2019). "Aging WT mice were insulin resistant, as indicated by homeostatic model assessment–insulin resistance (HOMA-IR) scores." (PMID 31329158, 2019). "Animal experiments suggest that myocardial insulin resistance, which involves reductions in myocardial metabolism, insulin-stimulated eNOS activity, and insulin protection effects, co-occurs with systemic IR." (PMID 31461405, 2019). "To elucidate the mechanism through which Nifu improves PA-induced insulin resistance, we monitored the levels of key proteins involved in the insulin pathway." (PMID 35540668, 2019). "These proinflammatory markers, as well as CRP, are suggested to induce insulin resistance and gluconeogenesis, subsequent hyperglycemia, and attenuate insulin signaling and sensitivity through insulin receptor substrate phosphorylation." (PMID 31143476, 2019). "Insulin sensitivity markers were calculated from basal endpoint serum glucose and insulin levels, of which homeostasis model assessment-estimated insulin resistance (HOMA-IR) showed significant differences in GotoK group compared to Wistar (p < 0.05)." (PMID 30736394, 2019). "On the other hand, chronic leptin administration inverts insulin resistance in the high-fat diet-induced insulin resistant Wistar rats." (PMID 31013835, 2019).